INS (insulin)
Diseases named in the same sentence as INS in open-access papers (continued):
Sharing a sentence is not in itself a finding about the gene and the disease.
Obesity (continued). "We also studied the markers for insulin and glucose metabolism and diet-induced obesity." (PMID 39567934, 2024). "In addition, the expansion of white adipose tissue is related to a changed microenvironment in obesity, which impairs insulin signaling, reduces insulin-stimulated glucose transport activity, and accelerates beta cell dysfunction." (PMID 38564266, 2024). "Further evaluation of the effects of miR-548ag inhibitor in improving the body’s glucose tolerance and insulin sensitivity will provide a theoretical basis for miR-548ag to become a candidate drug target for the clinical treatment of obesity and related metabolic diseases." (PMID 38424257, 2024). "Increasing evidence indicates that TCM, as a novel autophagy enhancer, may improve hepatic steatosis and insulin sensitivity in HFD-induced obesity." (PMID 38532480, 2024). "Furthermore, as expected, we also detected higher levels of insulin in MUO patients compared to HC, associated with obesity and inflammation." (PMID 38904913, 2024). "Mice with deficient Gnai2 signaling do not develop obesity despite a high-fat diet and show enhanced insulin sensitivity." (PMID 39484291, 2024). "According to the authors, ALS-L1023 may inhibit obesity and improve insulin sensitivity in part by inhibiting hepatic lipid accumulation via hepatic PPARα activation." (PMID 38675115, 2024). "The mechanisms of the protective effects of E2 against obesity are still being elucidated, but they may involve regulation of glucose-insulin homeostasis and leptin, affecting food intake and energy expenditure." (PMID 38883397, 2024). "The accumulation of excess fat and lipid metabolism disorders from obesity leads to insufficient insulin secretion or decreased insulin sensitivity, resulting in increased blood glucose levels in animals and ultimately leading to the occurrence and development of DM." (PMID 39118186, 2024). "As one of the most common side effects of insulin treatment remains significant weight gain, combining it with leptin-neutralizing antibodies would restore leptin sensitivity and prove beneficial for the management of obesity in type 2 DM." (PMID 38707092, 2024). "All 30 individuals had obesity (25 had severe obesity): 13 started insulin at the time of T2D diagnosis, 17 started insulin after HbA1c rose to 8% at a median time of 21 (range, 2-53) months postdiagnosis, and 4 discontinued insulin with subsequent HbA1c less than 8% (eFigure in Supplement 1)." (PMID 38231515, 2024). "However, the obesity paradox was much less marked in patients with DM treated with insulin and it disappeared in those with poor glycaemic control as defined by HbA1c levels > 7.5%." (PMID 37608126, 2024). "Multiple adipokines have been described to play a role in the resistance to insulin and in the maintenance of the chronic inflammation detected in obesity patients and could be classified as inflammatory mediators." (PMID 38731880, 2024). "A German study found that children with obesity showed higher growth at birth than their normal-weight counterparts and had an accelerated growth rate thereafter, which was associated with increased levels of IGF-1, insulin, and leptin in these children." (PMID 38398863, 2024). "Although the patients in this case series were on doses of a GLP-1 RA approved for treating T2DM, which are lower than the doses recommended for treating obesity, the doses used may still improve insulin sensitivity." (PMID 38539310, 2024). "Reduced insulin sensitivity in the body is the main determinant of obesity." (PMID 39731011, 2024). "The administration of recombinant FGF21 protein to mice fed an ob/ob, db/db, or high-fat diet (HFD), or obese Zucker diabetic fatty (ZDF) rats, has been shown to result in a significant reduction in obesity, lower blood glucose and triglyceride levels, and improved insulin sensitivity." (PMID 39902162, 2024).
Obesity (continued). "Additionally, increased levels of circulating insulin and insulin-like growth factor 1 (IGF1), typically associated with high BMI and obesity, positively influence aromatase activity in the adipose tissue." (PMID 39253073, 2024). "Also, obesity-induced chronic inflammation and disruptions of insulin and leptin signaling can result a disproportionate or hyper-inflammatory response, which, together with elevated ferritin levels, can be a direct cause for ARDS and cytokine storm." (PMID 38822415, 2024). "First, the insulin sensitivity is different between men and women with obesity." (PMID 38501152, 2024). "Obesity, characterized by excessive accumulation of adipose tissue leading to chronic low-grade inflammation, leptin and insulin resistance, and altered activity of the hypothalamic-pituitary-adrenal (HPA) axis, potentially triggering depressive symptoms directly or indirectly." (PMID 39394060, 2024). "PTH can influence lipid levels through its effects on calcium and activation of vitamin D in the kidney, but it can have some more direct effects on insulin resistance, adipose tissue metabolism, lipolysis, and obesity development, as well as lipid metabolism in the liver." (PMID 38412162, 2024). "We observed that maternal age at delivery ≥35 years (29.2% VS 17.1%, P = 0.011), overweight (37.5% VS 20.5%, P < 0.001) and obesity (12.5% VS 3.8%, P < 0.001) were significantly more prevalent in the women treated with insulin, compared to those managed through diet-and-exercise alone." (PMID 37946069, 2024). "Moreover, Akkermansia, in particular, has been highlighted for its role in obesity modulation through probiotic supplementation, improving inflammation, preventing metabolic disorders, and enhancing insulin sensitivity and glucose homeostasis." (PMID 39554352, 2024). "Recently, insulin resistance (IR), which is the dysfunction to utilize insulin of tissue cells and always accompany hyperinsulinemia, has been proven to be associated with lots of metabolic diseases, including CVD, dyslipidemia, obesity, and type 2 diabetes." (PMID 39309107, 2024). "Moreover, dysfunctional Langerhans islets and insulin secretion have been related to altered intercellular communications via Connexin36 (Cx36) gap junctions, which are downregulated in obesity and prediabetes." (PMID 38667278, 2024). "Increased expression of NEP was reported in plasma and metabolic tissues such as liver, kidney, epididymal, mesenteric and perirenal fat of mice with diet-induced obesity, its expression level correlated with decreased insulin sensitivity and reduced beta cell function." (PMID 38763496, 2024). "A diet with high DII may facilitate obesity by enhancing more insulin secretion, which may reduce fat oxidation and increase carbohydrate oxidation, therefore, such a diet could increase fat storage, abdominal obesity and enhanced risk of MetS25,58." (PMID 38263222, 2024). "Obesity compromises insulin efficiency in the body, resulting in higher blood sugar levels." (PMID 38976691, 2024). "Therefore, this approach provides a unique and powerful model to explore the relationships between obesity, fatty liver, and insulin action." (PMID 38656127, 2024). "IR could be defined as reduced insulin sensitivity in target organs, which represents the comorbidity of a sequence of metabolic abnormalities, such as obesity, hyperglycemia, and dyslipidemia." (PMID 38952394, 2024). "Probiotics may improve insulin sensitivity, decrease fat absorption, and increase energy expenditure—all of which are advantageous for controlling weight and preventing obesity." (PMID 38542720, 2024). "Our study findings suggest significant differences in the prevalence of complications and comorbidities and treatments for Black patients with T2D compared to White and Hispanic patients, with Black patients having higher rates of micro- and macrovascular complications, obesity, and insulin use." (PMID 38667608, 2024).
Obesity (continued). "Impaired endothelium-dependent vasodilation and fibrinolytic dysfunction—generated by hyperglycaemia, insulin resistance, abnormal insulin signalling, chronic inflammation and obesity-derived metabolic derangements—project the foreseeable emergence of cerebrovascular abnormalities." (PMID 38792441, 2024). "Moreover, there is little understanding of the relationship between liver lipid storage and insulin action in a setting of metabolically healthy obesity." (PMID 38656127, 2024). "In rodent models of diet-induced obesity, methionine restriction has shown improvements in body weight gain, glucose metabolism, and insulin sensitivity through a communication mechanism between the adipose tissue and the skeletal muscle, involving the release of the adiponectin." (PMID 38732510, 2024). "Moreover, AgRP-ATF4 KO mice are resistant to high-fat diet (HFD)-induced obesity, insulin resistance, and liver steatosis and under cold stress maintain a higher body temperature." (PMID 39125332, 2024). "Anti-obesity and anti-diabetic effects of mifepristone have been observed in both in humans and mice For example, short-term treatment with mifepristone improved adipose and hepatic insulin sensitivity in obese human patients with hyperglycemia." (PMID 38994975, 2024). "Lp(a) concentrations were similar in women with obesity and high and normal concentrations of insulin (19.9 mg/dl vs. 18.6 mg/dl), but men with obesity and hyperinsulinaemia had significantly lower Lp(a) levels than did men with obesity and normo-insulinaemia (7.9 mg/dl vs. 29.4 mg/dl)." (PMID 39210428, 2024). "Several acute studies conducted with healthy, normal-weight participants and participants with obesity showed small increases in blood glucose and insulin concentrations after oral or intragastric administration of various doses of xylitol (7 to 50 g of xylitol in 250–300 mL water)." (PMID 38474749, 2024). "While this may be the case in obesity-related T2D, this notion is challenged by the observation that various populations have varying degrees of insulin secretory capacity and IR." (PMID 38338783, 2024). "The following narrative review describes a unifying hypothesis for the pathophysiology of energy-dense diets, insulin resistance, oxidative stress, and impairment of mitochondrial function during the development of obesity." (PMID 39063184, 2024). "However, thereis a lack of human research investigating the relationship between fasting GLP-1 and glycemichomeostasis, obesity, insulin sensitivity, macronutrients, and dietary patterns." (PMID 38686701, 2024). "Furthermore, chronic inflammation induced by obesity not only affects insulin sensitivity but also promotes oral immune microenvironment disorders, ultimately exacerbating the severity of periodontitis." (PMID 38970059, 2024). "Research suggests that Phascolarctobacterium may improve obesity, insulin sensitivity, adipose tissue inflammation, and atherosclerosis by beneficially altering gut microbiota composition." (PMID 39394090, 2024). "In regard to this idea of personalized or precision nutrition, it is noteworthy that low-carbohydrate diets appear to be especially superior to low-fat diets in individuals who are insulin resistant or have high insulin secretion, which is common in people with obesity." (PMID 38814519, 2024). "Indeed, our findings indicated that hepatic-specific deletion of SELENOS accelerated the onset and progression of obesity, impaired glucose tolerance and insulin sensitivity, and increased hepatic TG and diacylglycerol (DAG) accumulation." (PMID 38172976, 2024). "In prepubertal children, African Americans displayed 42% lower insulin sensitivity than non-Hispanic Whites, with obesity, visceral fat, and ethnicity being independent risk factors." (PMID 39125938, 2024).
Obesity (continued). "Furthermore, a considerable decline in serum insulin levels was observed among participants with overweight or obesity following short- and long-term supplementation with low or high doses of SIL." (PMID 38671838, 2024). "In individuals with obesity, serum insulin levels may be increased due to peripheral insulin resistance." (PMID 38383709, 2024). "In vivo, we examined whether the BCAA catabolism in ATMs was altered in high-fat diet-induced obesity mice, and if BCAA supplementation would influence obesity, glucose tolerance, insulin sensitivity, adipose tissue inflammation and ATMs polarization in mice." (PMID 39267003, 2024). "Accumulating data from preclinical and experimental studies also support that melatonin may have beneficial effects on insulin signaling, adipocyte differentiation, and lipid metabolism in obesity, as well as inflammation in diabetes and related comorbidities." (PMID 38534314, 2024). "As TPP is potentially exacerbated by higher androgen and insulin levels, we suspect that with increasing rates of obesity and polycystic ovary syndrome, the incidence of TPP among adolescents may increase." (PMID 38770225, 2024). "Indeed, obesity in our volunteers was accompanied by greater amounts of visceral fat; reduced metabolic flexibility, as measured by the ability of insulin to increase RER; and by a 2- to 3-fold greater IC50 for suppression of adipose tissue palmitate release." (PMID 38602778, 2024). "Notably, sucralose-fed rats had the highest glucose (151.5 mg/dL), insulin (6.44 ng/mL), and leptin (25.54 ng/mL) levels, indicating a pronounced impact on obesity-related parameters." (PMID 39449954, 2024). "In Caucasians living with overweight/obesity, interrupting sitting with light walking for 2 to 5-min every 20 to 30-min attenuated postprandial glucose iAUC by 28% to 32% and insulin iAUC by 15% to 37%." (PMID 37950762, 2024). "It has been shown that the circadian rhythm disruption experienced by healthcare professionals as a result of working night shifts causes many negative health consequences, such as impaired glucose tolerance, decreased insulin sensitivity, obesity, cardiometabolic diseases, and cancer." (PMID 39125285, 2024). "Metabolite modifications that arose after 14 weeks of HFHSD could be a consequence of resistance to insulin and may reflect installed metabolic adaptation to obesity." (PMID 38542714, 2024). "Furthermore, the causal effects decreased considerably after including obesity (BMI), alcohol intake frequency, SHBG, hyperandrogenemia, and fasting insulin in the multivariable MR analysis." (PMID 38318294, 2024). "A more comprehensive metabolic assessment of the immune system in children with obesity, particularly via longitudinal studies, is needed to better understand the role of immune cell metabolism in the progression from a healthy insulin-sensitive state toward glucose intolerance." (PMID 38680993, 2024). "As a regulatory component of the m6A-methyltransferase machine, WTAP functions as a recruiter to drive the METTL3-METTL14 complex to its mRNA or lncRNA targets, and knockdown of WTAP has been shown to protect from diet-induced obesity, leading to improved insulin sensitivity." (PMID 39054531, 2024). "Thus, in a normal individual, in response to a reduction in insulin sensitivity (obesity, pregnancy, puberty), the β cells will compensate with greater insulin response — movement “up the curve”." (PMID 38299589, 2024). "Consequently, Med1 MKO mice are resistant to high-fat diet (HFD)-induced obesity and display enhanced insulin sensitivity and improved glucose tolerance." (PMID 38690566, 2024). "Adipokines are molecules secreted by adipocytes that play an important role in body weight control, lipid metabolism, insulin sensitivity, inflammation, vascular function, and immune regulation; however, their production is altered in obesity due to excess body fat." (PMID 39334752, 2024).
Obesity (continued). "Brain volume changes are primarily attributed to insulin resistance common in obesity, which hinders insulin transport to the brain, impairs glucose utilization by neuronal cells, and ultimately results in abnormalities in frontal axon and myelin structures, leading to cerebral atrophy." (PMID 38840158, 2024). "Moreover, EL levels have been inversely related to obesity and other markers of cardiometabolic diseases such as elevated triglycerides, glucose, and insulin levels." (PMID 39770115, 2024). "Initially, various indicators related to obesity were identified, such as BMI, triglycerides, fasting insulin, and T2D, which could potentially function as mediators linking television viewing and the occurrence of depression." (PMID 38424581, 2024). "In addition, systemic elevation of Gln improves insulin sensitivity and restores glucose homeostasis in a mouse model of obesity." (PMID 38799425, 2024). "Pin1 acts as a key regulator of the insulin signaling pathway, and Pin1 knockout mouse models exhibit resistance to fatty diet-induced obesity, highlighting the important role of Pin1 in adipogenesis and obesity." (PMID 39125345, 2024). "The beneficial effect of inositol on obesity and related disorders may be explained by its involvement in insulin signaling and improving insulin sensitivity." (PMID 38370063, 2024). "Impaired insulin signaling in the hypothalamus, a region that regulates energy balance and appetite, may also contribute to metabolic disorders such as T2DM and obesity, both of which elevate the risk of cognitive decline." (PMID 39596023, 2024). "Furthermore, together with the complementary CROSSYS clinical intervention study, CROSRAT will offer new information on the mechanisms by which exercise prevents the development of obesity-induced impairments in insulin sensitivity in various tissues." (PMID 38651416, 2024). "Accumulated evidence indicates that hormonal disturbance, insulin resistance, and inflammation may all play a role in the development of ovulation disorders in individuals with obesity." (PMID 38333108, 2024). "Also, NUPR1 is related to the degradation of insulin storages and subsequent secretion during inflammatory and obesity-related tissue stress." (PMID 39102232, 2024). "Evidence indicated that abnormal blood lipids might lead to insulin resistance in peripheral tissues, which in turn affects fat metabolism in the liver after eating, leading to overweight and obesity." (PMID 38732585, 2024). "Building on our previous study, we found that the insulin sensitivity of mice treated with zeaxanthin was enhanced; therefore, we speculate that obesity can induce IR, and obesity-induced IR may be improved with the intervention of zeaxanthin." (PMID 39517172, 2024). "However, in insulin-resistant genetic models of obesity, such as the ob/ob and db/db mice, and in high-fat diet-induced obese mice, Treg cells in adipose tissue are markedly diminished." (PMID 39337290, 2024). "IMCL in human skeletal muscles is associated with decreased insulin sensitivity independent of the overall obesity and fat distribution." (PMID 39769002, 2024). "ATP5F1B abundance was increased in SAT samples from insulin-resistant patients with obesity compared to lean insulin-sensitive controls, demonstrating an important role in the development of obesity-related IR and inflammation due its involvement in energy and free fatty acid metabolism." (PMID 38703299, 2024). "Furthermore, NMN aids in the prevention of obesity and metabolic syndrome by modulating metabolic pathways, enhancing lipolysis, and improving insulin sensitivity." (PMID 39408861, 2024). "Similarly, oxidative stress and damage are present in the hypothalamus of obesity models and hypothalamic oxidative stress aggravates obesity-induced insulin and leptin resistance." (PMID 38397850, 2024). "Knockout of Olfr734 improves glucose tolerance and insulin sensitivity in obesity." (PMID 39872218, 2024).